CASC8 (cancer susceptibility 8)
Synonyms: LINC00860; CARLo-1; CARLO1
Gene: Long non-coding RNA gene on chromosome 8 (127,289,667 to 127,482,139, reverse strand). Ensembl gene ENSG00000246228.
Diseases named in the same sentence as CASC8 in open-access papers:
CASC8 is named in the same sentence as 39 diseases in open-access papers, as found by Europe PMC text mining. Sharing a sentence is not in itself a finding about the gene and the disease. The quoted sentences say what the papers report.
pancreatic cancer (14 papers, 2019 to 2025). "A genome-wide association study (GWAS) of 9,040 patients with pancreatic cancer has identified CASC8 as a risk factor for the incidence and genetic susceptibility of pancreatic cancer." (PMID 38012210, 2023). "The abnormalities in CASC8 are often closely associated with esophageal squamous cell carcinoma, non-small cell lung cancer, colon cancer, and pancreatic cancer." (PMID 36672865, 2023). "In pancreatic cancer, CASC8 is specifically expressed at a high level and associated with poor prognosis, which is consistent with our results." (PMID 34854360, 2021). "CASC8 also overlaps with a PC-associated lncRNA, suggesting that genetic variants in CASC8 may contribute to the transcriptional program of pancreatic tumor cells." (PMID 33517887, 2021). "We further analyzed the effect of CASC8 gene polymorphism on pancreatic cancer." (PMID 32582694, 2020). "The analysis revealed that CASC8 expression was higher in pancreatic cancer samples compared to controls (Log2FC = 1.245, adjusted P = 2.29E-56)." (PMID 39865281, 2025). "Among them, CASC8 was significantly correlated with the incidence and survival prognosis of pancreatic cancer." (PMID 38012210, 2023). "The results showed that the expression of CASC8 in pancreatic cancer was significantly higher than that in normal pancreatic tissue." (PMID 37713870, 2023). "CASC8 expression was elevated in 17 of 19 pancreatic cancer samples, of which 7 were moderately differentiated and 10 were moderately-poorly differentiated according to AJCC Cancer Staging Manual/Edition 8th." (PMID 37713870, 2023). "We found that CASC8 was upregulated in pancreatic cancer cells (Mia-PaCa-2, CFPAC-1, and Panc-1 cells) and AC096733.3 was in low expression compared with HPNE cells, which were with the same expression profile with TCGA data." (PMID 34956238, 2021). "A study on pancreatic cancer has demonstrated that CASC8 may serve as an effective prognostic marker and can indicate the proportion of immune infiltration in high-risk tumors." (PMID 39865281, 2025). "CASC8, DNMBP-AS1, LINC00941, TM4SF1-AS1, and UCA1 expression was positively correlated with risk scores, indicating that they are risk factors for pancreatic cancer; in contrast, SNHG10 and SOCS2-AS1 were negatively correlated, thus serving as protective factors for pancreatic cancer." (PMID 36871072, 2023). "Five lncRNAs (LINC00941, UCA1, CASC8, TM4SF1-AS1, and DNMBP-AS1) were more strongly expressed in the high-risk group than in the low-risk group, suggesting that they are the potential risk factors for pancreatic cancer." (PMID 36871072, 2023). "For example, the correlation coefficient between Lnc-PQLC1-10 and CASC8 was more than 0.5, suggesting a potential biological relevance might exist between them in the development of pancreatic cancer." (PMID 36186449, 2022). "The results showed that CASC8 was overexpressed in all pancreatic cancer lines, which indicated that CACS8 may also play a key role in promoting pancreatic cancer progression." (PMID 34956238, 2021). "CASC8 and LYPLAL1-AS1 were differentially expressed in pancreatic cancer tissues and normal pancreatic tissues." (PMID 37713870, 2023). "Under the LASSO regression and multivariate Cox regression analysis, five lncRNAs(ZNF236-DT, CASC8, PAN3-AS1, SH3PXD2A-AS1, LINP1) of them were selected to establish the novel prognostic FRLS for predicting the OS of patients with pancreatic cancer." (PMID 35330729, 2022). "For instance, PDX1 was involved in both CASC8-related and VPS9D1-related networks, and also recognized as a key regulator and a potential target in pancreatic cancer." (PMID 31720124, 2019). "Survival analysis of pancreatic cancer samples showed that low expression of UCA1, TM4SF1-AS1, LINC00941, DNMBP-AS1, and CASC8 improved OS more than high expression, whereas high expression of SNHG10 and SOCS2-AS1 improved OS more than low expression (P < 0.001)." (PMID 36871072, 2023).
pancreatic cancer (continued). "The present study implicates that several ferroptosis-related lncRNAs(ZNF236-DT, CASC8, PAN3-AS1, SH3PXD2A-AS1, LINP1) may serve as independent prognostic biomarkers for pancreatic cancer." (PMID 35330729, 2022). "In summary, we identified the prognostic ferroptosis-related lncRNAs(ZNF236-DT, CASC8, PAN3-AS1, SH3PXD2A-AS1, LINP1) in pancreatic cancer and these lncRNAs may serve as therapeutic targets for pancreatic cancer." (PMID 35330729, 2022).
colorectal cancer (12 papers, 2015 to 2025). A primary or metastatic malignant neoplasm that affects the colon or rectum. "CASC8 is associated with the risk of multiple cancers, including non-small cell lung cancer, retinoblastoma, esophageal squamous cell carcinoma, and colorectal cancer, and has been found to be highly expressed in hepatoma cells like MIA PaCa-2." (PMID 38408075, 2024). "A meta-analysis including 22 studies (47,003 cases and 45,754 controls) evaluated the rs6983267 of CASC8 in colorectal cancer, suggesting that the rs6983267 G > T polymorphism is a risk factor in Asians, Europeans, and Americans with European ancestry." (PMID 32582694, 2020). "Recent evidence suggested that CASC8 gene polymorphism, such as rs7837328, rs7014346, rs6983267, play important roles in various cancers including prostate cancer, breast cancer, colorectal cancer (CRC), and gastric cancer." (PMID 27249003, 2016). "CDKN2B-AS1 and TMEM220-AS1 were significantly downregulated in colon cancer, whereas LINC02257, PCAT1, and CASC8 were significantly upregulated in colorectal cancer." (PMID 41144378, 2025). "Only the CASC8 has been reported in the multiple malignant tumor such as colorectal cancer, lung cancer, and hepatocellular carcinoma." (PMID 34956238, 2021). "A relationship between the CASC8, SMAD7 genes, and risk of colorectal cancer were analyzed in a meta-analysis including 90 studies (168,471 cases and 163,223 controls)." (PMID 32582694, 2020). "In addition, numerous colorectal cancer associated lncRNAs, such as CCAT6 (MYCLo-2), CASC8 (CARLo-1), CASC21 (CARLo-2), PRNCR1 (CARLo-3), PCAT2 (CARLo-4), and CASC11 (CARLo-7), have been identified." (PMID 30441811, 2018). "While the exact contributions of ATF1, DUSP10 and CASC8 in TA remain to be further elucidated, our findings further support that genes involved in colorectal cancer may also be involved in tooth development and provide additional insights into deciphering the complex etiology of the condition." (PMID 29445242, 2018).
lung carcinoma (10 papers, 2016 to 2024). "For the first time, our study showed that lncRNA CASC8 rs10505477 polymorphism was significantly related to lung cancer susceptibility, platinum-based chemotherapy response and toxicity." (PMID 27249003, 2016). "In present study, we evaluated the relationship of CASC8 rs10505477 to lung cancer susceptibility, platinum-based chemotherapy response, and toxicity." (PMID 27249003, 2016). "In summary, for the first time, we explored the effect of CASC8 rs10505477 polymorphism on lung cancer susceptibility, platinum-based chemotherapy response, and toxicity." (PMID 27249003, 2016). "The relationship between lncRNA CASC8 rs10505477 polymorphism and lung cancer susceptibility was determined after sex and age adjusted." (PMID 27249003, 2016). "First, despite that strong correlations between rs10505477 and lung cancer risk, platinum-based chemotherapy response and toxicity were observed, how this genetic variant influence CASC8 still need further investigation." (PMID 27249003, 2016). "For example, genetic variant, rs10505477 in LncRNA CASC8 was associated with the risk of lung cancer and could predict the response of lung cancer patients to platinum-based drug therapy." (PMID 38877481, 2024). "In a meta-analysis, the long noncoding RNA cancer susceptibility candidate 8 (CASC8) was found to be a cancer susceptibility gene closely related to lung cancer, but its functions in lung cancer are unknown." (PMID 33391435, 2021). "Interestingly, cancer susceptibility candidate eight (CASC8) is a lncRNA that has been reported to be involved in various of cancers by its gene polymorphism, including lung cancer." (PMID 31720124, 2019). "Thus, lncRNA CASC8 rs10505477 could serve as a possible risk marker for diagnosing lung cancer, and could be used to forecast the response and toxicity of platinum-based treatment in lung cancer patients." (PMID 27249003, 2016). "Thus, the SNP rs10505477 in CASC8 may serve as an underlying risk marker for detecting and diagnosing lung cancer, and could be used to determine the response and toxicity of platinum-based chemotherapy in lung cancer patients." (PMID 27249003, 2016). "So far, there is no study investigating the clinical significance of lncRNA CASC8 rs10505477 in lung cancer susceptibility and treatment." (PMID 27249003, 2016). "Taken together, we speculate that, probably, lncRNA CASC8 rs10505477 polymorphism could affect the efficacy and toxicity of platinum-based chemotherapeutic drugs through POU5F1B-OCT-3/4-ABCG2 axis in lung cancer patients." (PMID 27249003, 2016). "However, to our best knowledge, the implication of lncRNA CASC8 rs10505477 in lung cancer remains unclear." (PMID 27249003, 2016). "CASC8 rs10505477 failed to be statistically related to lung cancer risk." (PMID 27249003, 2016). "In previous studies on lung cancer-related lncRNAs, LINC01842 was considered to regulate lung cancer cell proliferation in a ceRNA pattern with CASC8 and VPS9D1-AS1." (PMID 37781694, 2023).
bladder cancer (9 papers, 2018 to 2021). "CASC8 is also involved in the regulation of the glycolysis in bladder cancer cells through modulating expression of the fibroblast growth factor receptor 1 (FGFR1)." (PMID 33123468, 2020). "Through attenuating the glycolysis, CASC8 was reported to suppress the proliferation of bladder cancer cells." (PMID 31398859, 2019). "Furthermore, the lncRNA CASC8 suppresses the proliferation of bladder cancer cells by downregulating glycolysis." (PMID 32875717, 2020). "Overexpression of CASC8 through interacting with FGFR1 and inhibiting FGFR1-mediated LDHA phosphorylation could suppress glycolysis in bladder cancer cell." (PMID 33123468, 2020).
esophageal squamous cell carcinoma (8 papers, 2020 to 2025). Esophageal squamous cell carcinoma (ESCC) is a type of esophageal carcinoma (EC) that can affect any part of the esophagus, but is usually located in the upper or middle third. "In esophageal squamous cell carcinoma tissues, the expression of LncRNA cancer susceptibility candidate 8 (CASC8) was higher than that in the control tissues and positively associated with the poor prognosis of patients." (PMID 37365581, 2023). "LncRNA cancer susceptibility candidate 8 (CASC8) was highly overexpressed in esophageal squamous cell carcinoma tissues in an ALKBH5-mediated m6A modification dependent manner." (PMID 37365581, 2023). "In esophageal squamous cell carcinoma, ALKBH5-mediated m6A removal is linked to regulating the lncRNA CASC8, which enhances cell growth and cisplatin resistance in ESCC." (PMID 38125749, 2023). "Here, we identified the molecular mechanisms of lncRNA Cancer Susceptibility Candidate 8 (CASC8) in promoting the malignancy of esophageal squamous cell carcinoma (ESCC)." (PMID 35982900, 2022). "In esophageal squamous cell carcinoma, the upregulation of the lncRNA cancer susceptibility candidate 8 (CASC8) through ALKBH5-mediated m6A demodifications stabilizes the CASC8 transcript, thereby negatively modulating the caspase-3 apoptotic pathway." (PMID 41373022, 2025). "CASC8 is an oncogene that can delay the progression of esophageal squamous cell carcinoma by binding directly to hnRNPL and preventing it from being degraded by ubiquitin-mediated processes." (PMID 36672865, 2023). "A previous study has proven the effect of the CASC8 rs1562430 polymorphism on esophageal squamous cell carcinoma (ESCC) susceptibility and discovered that functional polymorphisms in CASC8 rs1562430 A > G may influence an individual’s susceptibility to ESCC." (PMID 36983670, 2023). "However, the effect of CASC8 SNPs on esophageal squamous cell carcinoma (ESCC) remains unclear." (PMID 32875717, 2020).
non-small cell lung carcinoma (8 papers, 2021 to 2024). A group of at least three distinct histological types of lung cancer, including non-small cell squamous cell carcinoma, adenocarcinoma, and large cell carcinoma. "In the Cancer Genome Atlas database, the expression of CASC8 was significantly higher in non-small cell lung cancer than in adjacent normal tissues, and high expression of CASC8 was associated with poor prognosis in patients with lung adenocarcinoma." (PMID 33391435, 2021). "Silencing CASC8 inhibited the proliferation, migration, and invasion of non-small cell lung cancer cells and promoted their sensitivity to osimertinib." (PMID 35330729, 2022). "The low expression of CASC8 reduces the malignant biological behavior in non-small cell lung cancer." (PMID 34854360, 2021). "Silencing CASC8 inhibited proliferation, migration, and invasion in non-small cell lung cancer cell lines." (PMID 33391435, 2021). "Moreover, in non-small cell lung cancer cells, through Western blotting, researchers found that when CASC8 was knockdown, the level of FOXM1 protein decreased." (PMID 34199840, 2021). "Our study revealed for the first time that silencing CASC8 inhibited the proliferation, migration, and invasion of non-small cell lung cancer cells and promoted their sensitivity to osimertinib, suggesting that CASC8 is closely related to the occurrence and development of non-small cell lung cancer." (PMID 33391435, 2021). "Besides, inhibiting CASC8 led to decreased development in non-small cell lung cancer and enhanced sensitivity against chemotherapy, implying CASC8 might be a novel target for cancer treatment in the future." (PMID 36186449, 2022).
gastric cancer (7 papers, 2015 to 2023). A primary or metastatic malignant neoplasm involving the stomach. "A study on a Chinese population found that rs10505477 GA heterozygote in CASC8 was associated with a significantly lower survival rate in gastric cancer." (PMID 32582694, 2020). "SNPs in the CASC8 gene, such as rs7837328, rs6983267, and rs7014346, are correlated with the risk of cancer, including prostate, breast, colorectal, and gastric cancers." (PMID 32875717, 2020). "It was reported that the SNP rs10505477 in CASC8 gene is related to risk of several solid tumor malignancies, such as CRC, gastric cancer and invasive ovarian cancer." (PMID 27249003, 2016). "The SNP rs10505477, located in the intron of lncRNA CASC8, showed strong association with the risk of CRC and the prognosis of gastric cancer." (PMID 27249003, 2016).
prostate carcinoma (7 papers, 2016 to 2024). A carcinoma that arises from epithelial cells of the prostate gland. "CASC8, rs6983267, is also associated with increased susceptibility to prostate cancer, in addition to CRC, but the molecular mechanism of association is under investigation." (PMID 35893034, 2022). "Furthermore, the GT haplotypic structure of rs10505477‐rs6983267 variants with 5 kb distance on the CASC8 gene is associated with colorectal and prostate cancers in European population." (PMID 39031745, 2024). "Except for one protective variant (MTHFR rs1801133) for prostate cancer (OR = 0.684, 95% c.i.=0.565–0.828), six of the seven variant (in MGMT, XRCC1, OGG1, ERCC2 and CASC8) showed risks for prostate cancer." (PMID 26967244, 2016). "The results of gene expression showed that CASC8 gene expression is significantly different from adjacent normal tissues in colorectal and prostate cancers." (PMID 39031745, 2024). "The CASC8 gene is responsible for expressing a lncRNA (long non-coding RNA) that plays an important role in the regulation of MYC, which is related to susceptibility to various cancers, such as breast, colorectal, and prostate cancers." (PMID 35741800, 2022).
breast carcinoma (5 papers, 2015 to 2024). "Among these, four ncRNAs (CASC8, GRIK1-AS1, LINC02188, and ROCR) exhibit diminished expression levels in breast cancer, while one lncRNA (LINC00511) displays elevated expression in breast cancer." (PMID 38408075, 2024). "The data show an upregulation of breast cancer related genes in T1 and C1 relative to 10A, including LRATD2, PCAT1, CASC19, CASC8, POU5F1B, PVT1 and MYC on chromosome 8." (PMID 38076897, 2024).
retinoblastoma (5 papers, 2022 to 2025). A malignant tumor that originates in the nuclear layer of the retina. "It is stated that overexpression of CASC8 as well as decreased production of miR34a are associated with cell proliferation and thus with retinoblastoma." (PMID 41150792, 2025). "CASC8 was found highly expressed in retinoblastoma, contributing to retinoblastoma cell proliferation by upregulating miR34a methylation." (PMID 35197523, 2022). "It was reported that CASC8 promoted the proliferation of retinoblastoma cells via manipulating the methylation of miRNA-34a." (PMID 36186449, 2022).
pancreatic ductal adenocarcinoma (3 papers, 2022 to 2025). An infiltrating adenocarcinoma that arises from the epithelial cells of the pancreas. "This study aimed to confirm the existence of disulfidptosis in pancreatic ductal adenocarcinoma (PDAC) and elucidate the role of Cancer Susceptibility 8 (CASC8) in this process." (PMID 39865281, 2025). "For the first time, we analyzed the expression of CASC8 lncRNA in human pancreatic ductal adenocarcinoma cell lines and found an abundant isoform that was previously considered as the minor one in this type of cancer." (PMID 36038677, 2022).
colon cancer (2 papers, 2023 to 2025). "Notably, TMEM220-AS1, TMEM238L, SOX6, SMAD7, TCF7L2, and PYGL were significantly downregulated in colon cancer, whereas LINC02257, PCAT1, CASC8, and POU5F1B were significantly upregulated in colon cancer." (PMID 41144378, 2025).
colorectal adenoma (2 papers, 2021 to 2025). An adenoma that arises from the colon or rectum. "In a study of colorectal adenoma, two CASC8 SNPs (rs10505477 and rs6983267) were found to be associated with colorectal adenoma risk, especially in patients without a family history of colorectal cancer." (PMID 34199840, 2021).
endometrial cancer (2 papers, 2021 to 2024). Primary or metastatic malignant neoplasm involving the endometrium (mucous membrane that lines the endometrial cavity). "However, different target genes were observed as well, like CASC8, CASC11, and LINC01137 were only detected in EOC cells, indicating the different roles of these genes in tumorigenesis between endometrial cancer and EOC." (PMID 33815481, 2021).
medulloblastoma (2 papers, 2021 to 2022). A malignant, invasive embryonal neoplasm arising from the cerebellum. "The outlier with the highest number of fusion reads in medulloblastoma is sample 67 from the Group 3 subtype, with most of these reads originating from the PVT1--CASC8 linear fusion." (PMID 35804907, 2022). "Additional selected linear fusions in medulloblastoma that cannot be interpreted via read-through transcription are the TFG--ADGRG7 and the PVT1--CASC8." (PMID 35804907, 2022).
ovarian carcinoma (2 papers, 2020 to 2024). A malignant neoplasm originating from the surface ovarian epithelium. "The CASC8 rs10505477 variant is related to the development of numerous cancers including colorectal, gastric, and ovarian cancers." (PMID 32875717, 2020).